GLRA4 (glycine receptor alpha 4 (pseudogene))
Synonyms: GLRA4P
Gene: Transcribed unitary pseudogene on chromosome X (103,707,224 to 103,728,203, reverse strand). Ensembl gene ENSG00000188828.
Diseases named in the same sentence as GLRA4 in open-access papers:
GLRA4 is named in the same sentence as 6 diseases in open-access papers, as found by Europe PMC text mining. Sharing a sentence is not in itself a finding about the gene and the disease. The quoted sentences say what the papers report.
Intellectual disability (3 papers, 2016 to 2018). "Despite this, a recent genetic study has implicated GLRA4 in intellectual disability, behavioral problems and craniofacial anomalies." (PMID 29445326, 2018). "Interest in GlyR α4 has recently been rekindled by reports that GLRA4 in humans is potentially involved in intellectual disability, behavioral problems and craniofacial anomalies." (PMID 29445326, 2018). "A microdeletion at Xq22.2 implicates GLRA4 to be involved in intellectual disability and behavioural problems." (PMID 28775826, 2017). "We hypothesize that GLRA4 is involved in intellectual disability, behavioral problems and craniofacial anomalies as the second gene identified for X-linked syndromic intellectual disability at Xq22.2." (PMID 27506666, 2016). "The reduction of GLRA4 transcript levels in DGDP084 in the family coupled with its expression pattern in the brain suggest that GLRA4 is the plausible candidate gene for the clinical features observed in DGDP084 including intellectual disability, behavioral abnormalities, and craniofacial anomalies." (PMID 27506666, 2016). "Using an atypical microdeletion, which does not encompass PLP1, we implicate a novel gene GLRA4 involved in intellectual disability, behavioral problems and craniofacial anomalies." (PMID 27506666, 2016). "Our comparative deletion mapping and RT-qPCR results support the hypothesis that GLRA4 is a novel candidate gene for XLID and is likely involved in the intellectual disability, behavioral problems, and craniofacial anomalies seen in DGDP084." (PMID 27506666, 2016).
Cognitive impairment (2 papers, 2016 to 2023). Abnormal cognition is characterized by deficits in thinking, reasoning, or remembering. "A recent genetic study reported that the GLRA4 pseudogene locus on the X chromosome is potentially involved in cognitive impairment, motor delay and craniofacial anomalies in humans." (PMID 37217969, 2023). "The functional importance of GLRs and the observed patterns of expression of GLRA4 in the brain are consistent with a role in cognitive deficits and behavioral abnormalities observed in patient DGDP084." (PMID 27506666, 2016). "This suggests that GLRA4 is the plausible candidate gene for cognitive impairment, behavioral problems and craniofacial anomalies observed in DGDP084." (PMID 27506666, 2016). "We hypothesize that GLRA4 is a novel candidate gene for XLID and is likely involved in the clinical features observed in our patient including cognitive impairment, behavioral problems and speech delay." (PMID 27506666, 2016). "Our patient DGDP084 does not have hyperekplexia and it is possible that the cognitive impairment and unusual behaviors displayed by DGDP084 such as banging on windows and furniture may be due to reduced GLRA4 expression in the brain disrupting the composition of heteromeric GLRs." (PMID 27506666, 2016).
Pelizaeus Merzbacher Disease (2 papers, 2018 to 2023). "However, there are discrepant reports about GLRA4 implication in Pelizaeus Merzbacher Disease (PMD)." (PMID 37217969, 2023).
Anxiety (1 paper, 2023). Intense feelings of nervousness, tension, or panic often arise in response to interpersonal stresses. "Moreover, Glra4 mutant mice manifested several behavioral phenotypes such as increased anxiety-like behavior, decreased and delayed acoustic startle response, and enhanced social interaction in the home cage." (PMID 37217969, 2023).
GLRA4 also shares sentences with these, for which no sentence is quoted: hyperekplexia (1 paper); syndromic intellectual disability (1).